IGFBP5 (insulin like growth factor binding protein 5)
Diseases named in the same sentence as IGFBP5 in open-access papers (continued):
Sharing a sentence is not in itself a finding about the gene and the disease.
cancer (continued). "Several of the hallmarks of cancer, including sustained cell proliferation and resistance to apoptosis, result from dysregulation of genes, such as IGFBP5, that are key in developmental pathways and can thus facilitate aberrant hyperplasia." (PMID 36465383, 2022). "In low-grade invasive BC, ~50% of the cancer cells show well detectable protein levels of IGFBP5 in the cytoplasm." (PMID 36093095, 2022). "These and other functional roles which implicate IGFBP5 in the progression of different cancers will now be discussed." (PMID 36465383, 2022). "Identified by using tuberous sclerosis complex (TSC)-/- mouse embryonic fibroblasts, the IGFBP5-dependent feed back regulation of the PI3K/AKT pathway was also demonstrated to take place in cancer cells, including MCF-7 cells." (PMID 36093095, 2022). "Genes in the regulation of the insulin-like growth factor transport pathway have known functions in cancer proliferation and migration, including IGFBP5, PRSS23, SCG2, and SPP1." (PMID 35008167, 2021). "Mir-204-5p was found to be capable of inhibiting cancer progression by regulating the expression of TNRRSF12A, associated with angiogenesis, and IGFBP5, associated with cell cycle progression and proliferation." (PMID 35186709, 2021). "In cancer cells, direct high-affinity interaction between IGFBP5 and α2β1 integrin (aka ITGA2) has been reported." (PMID 34830489, 2021). "IGFBP5 is the most conserved of the IGFBPs and is frequently dysregulated in cancers and metastatic tissues." (PMID 32127912, 2020). "IGFBP5 as the most conserved of the IGFBPs, its different domains have different effects on tumorigenicity and metastasis of different human cancers." (PMID 32127912, 2020). "Because IGFBP5 had been shown to stimulate proliferation is related to the PI3K (phosphoinositol-3-kinase)/Akt pathway in cancers cells, we examined the Akt and pAkt proteins levels using WB after IGFBP5 silencing." (PMID 32127912, 2020). "And insulin-like growth factor binding protein 5 (IGFBP5) is the most conserved of the IGFBPs and is frequently dysregulated in cancers and metastatic tissues." (PMID 32127912, 2020). "We found that, by IHC score, LAT1 and IGFBP-5 were highly expressed in high-grade cancer lesions (26 of 68 specimens, 38.24%)." (PMID 31992742, 2020). "The expression level and functional differences of IGFBP5 in distinct cancer types and in the same tissue type suggests that there are still many mysteries about IGFBP5." (PMID 32127912, 2020). "IGFBP5 has been involved in regulating the growth and development of various types of cancers, but few studies have provided any deep understanding of IGFBP5 on GBM." (PMID 32127912, 2020). "Our results reveal that DIRC3 activates expression of the neighbouring Insulin Like Growth Factor Binding Protein 5 (IGFBP5) tumour suppressor gene to control gene expression programmes involved in cancer." (PMID 31881017, 2019). "This is similar to the effect of DIRC3 depletion and is consistent with our transcriptomic experiments showing that DIRC3 activates IGFBP5 to control shared gene expression programmes involved in cancer." (PMID 31881017, 2019). "We also discovered that DIRC3 functions as a new transcriptional regulator to activate its neighbouring IGFBP5 gene and control genome-wide expression programmes involved in cancer." (PMID 31881017, 2019). "This is important as dysregulated IGFBP5 transcriptional control can act as a driver of cancer growth and metastasis, regulating cell proliferation, differentiation and metabolism using both IGF1R-dependent as well as -independent mechanisms of action." (PMID 31881017, 2019). "qPCR showed that the expression of IGFBP5 mRNA was significantly lower in carcinoma samples than in paracarcinoma samples among all three pairs, with an average difference in expression of approximately 5.22-fold (p < 0.001)." (PMID 31886201, 2019).
cancer (continued). "Western blotting also showed significantly less IGFBP5 expression in carcinoma tissues than in paracarcinoma tissues." (PMID 31886201, 2019). "IGFBP5 has a unique function and mechanism of action and participates in several biological processes in carcinoma, such as cell proliferation, angiogenesis, cell migration and cell-cell adhesion, but these functions are bidirectional." (PMID 31886201, 2019). "Our data have shown that calcitriol treatment induced expression of IGFBP5 in ovarian bulk cancer cells, but inhibited IGFBP5 expression in CSCs." (PMID 29581858, 2018). "These two pathways play a pivotal role in understanding cancer progression and development of treatment strategies considering IGFBP5." (PMID 26569312, 2015). "The functional role of fluctuational IGFBP5 expression in origination and development of different types of cancer is still mysterious." (PMID 26569312, 2015). "IGFBP5, the most conserved member of the IGFBPs family, is frequently dysregulated in human cancers and metastatic tissues." (PMID 26010068, 2015). "IGFBP-5 is critically important in human cancer progression; and we have previously shown that RASSF1C is a binding partner of IGFBP-5." (PMID 25007054, 2014). "Within this locus, we identified Igfbp5 and Igfbp2 as the best candidate cancer modifier genes, members of the insulin-like growth factor binding protein family." (PMID 22973541, 2012). "In cancer cells, IGFBP-5 activated the caspase-8 signal transduction pathway, increased the structure sensitivity to TNF-α, and induced the internal apoptosis pathway." (PMID 19476635, 2009). "In cancer tissues, IGFBP5 resides mainly in the cytoplasm; however, in transfected cells, IGFBP5 is mainly located in the nucleus." (PMID 19341485, 2009). "Although studies showing the relationship between serum IGFBP-5 levels and cancer are limited, while IGFBP-5 expression has been reported to increase in pancreas tissues, it has also been demonstrated that low expression of IGFBP-5 in breast, renal and lung cancer tissues." (PMID 41303367, 2025). "Furthermore, the DEGs of cancer cells from clodronate-treated tumors (Wfdc18, Igfbp5, and Trf) corresponded to the marker genes of the Cancer_s6 cluster." (PMID 38169569, 2024). "The results revealed that IGFBP5 was positively correlated with different signaling pathways, including I-kappaB kinase/NF-kappB signaling, Proteoglycans in cancer, MAPK signaling pathway, HIF-1 signaling pathway, ECM-receptor interaction, Hippo signaling pathway." (PMID 38164271, 2024). "This may be a key mechanism by which IGFBP3, IGFBP5, and possibly other IGFBPs may regulate the balance between cell death and survival in response to some cancer therapies." (PMID 37088808, 2023). "IGFBP-5 targeting by miR-24-3p could be relevant in a number of cancers in which miR-24-3p has an oncogenic role, including lung, breast, and bladder cancer." (PMID 35597813, 2022). "Taken together these studies suggest IGFBP5 may be important for sensitizing cancer cells to platinum-based cytotoxic therapies." (PMID 36465383, 2022). "Additionally, recent advances addressing the role of IGFBP5 in resistance to cancer therapeutics will be discussed." (PMID 36465383, 2022). "Notably, IGFBP-2, IGFBP-3, and IGFBP-5 participate in a wide variety of ncRNA-regulated pathways, with both stimulatory and inhibitory effects on cancer cell functions." (PMID 35597813, 2022). "In sum, these data not only suggest that tumorally expressed IGFBP5 may serve as a useful marker to assess responsiveness of cancer cells to IGF1R inhibitors, but also that IGFBP5 is causatively involved in the acquisition of resistance to these drugs." (PMID 36093095, 2022). "The domains of IGFBP5 have differential activity in cancer as previously discussed, and MMPs and other proteins that cleave IGFBP5 could influence the impact of this protein has in cancer by increasing the prevalence of protein fragments." (PMID 36465383, 2022).
cancer (continued). "Understanding IGFBP5 activity in different contexts including cell type, differentiation status, microenvironment, or in conjunction with other pro-tumorigenic pathways will provide mechanistic insight into the role of IGFBP5 in cancer progression." (PMID 36465383, 2022). "Additionally, IGFBP5 possesses IGF-independent activities, which contribute to the complexity by which IGFBP5 interferes with cancer cell behavior." (PMID 36093095, 2022). "IGFBP5 expression was consistently lower in cell lines derived from ovarian, pancreatic and esophagogastric cancers, which is consistent with reports from a study of patient samples which reported low levels of IGFBP5 expression in cancer tissue relative to normal ovarian surface epithelium." (PMID 36465383, 2022). "This is another example pointing to the dual nature of IGFBP5 in cancer cell biology." (PMID 36093095, 2022). "Due to the similarities between IGFBP5 and the other IGFBPs, as well as the IGF binding CCN family, there may be compensatory mechanisms that have not yet been elucidated that contribute to the context-specific effects of IGFBP5 in cancer progression." (PMID 36465383, 2022). "Evidence for anti-tumorigenic, pro-tumorigenic, or undetermined functions of IGFBP5 in cancer." (PMID 36465383, 2022). "An in silico study revealed that higher IGFBP5 RNA was associated with poorer overall survival in luminal A, but not in luminal B cancer." (PMID 36093095, 2022). "Generation of cell lines that trap IGFBP5 in the nucleus by mutating the NLS resulted in increased growth and migration, indicating that subcellular localization of IGFBP5 is important in determining its role in cancer." (PMID 36465383, 2022). "Depending on the anti-cancer drug, IGFBP5 either sensitizes or de-sensitizes BC to such drugs." (PMID 36093095, 2022). "Extensive molecular profiling revealed that a number of components of the IGF signaling pathway, including insulin receptor substrate-2 (IRS2) and IGF-binding protein-5 (IGFBP5) among others, play key roles in determining the sensitivity of cancer cells to a humanized IGF1R antibody." (PMID 32391121, 2020). "IGFBP5 plays several outstanding roles in carcinogenesis to regulate cell growth, migration, and invasion during the development of cancer, but its function in the progression of cancer is controversial." (PMID 32801999, 2020). "Synchronous expression of two proteins may indicate the active contribution of the LAT1 mediated IGFBP-5 pathway in cancer cells." (PMID 31992742, 2020). "Altered levels of IGFBP-5 have been detected in many types of cancer." (PMID 32194505, 2020). "IGFBP-5 has been found to both inhibit and promote cancer cell growth in vitro." (PMID 32194505, 2020). "IGFBP-5 has been found to indicate a poor prognosis in patients with several types of cancer." (PMID 32194505, 2020). "Previous studies on the role of IGFBP5 in the proliferation of cancer cells are inconsistent." (PMID 32127912, 2020). "We hypothesize that downregulated IGFBP5 expression might release the binding domain of TNFR1 to restore apoptosis induced by TNF-α in cancer cells." (PMID 31886201, 2019). "Igfbp5, Enpp2, Ctsh, Lpl, and Tacc1 are the top five genes correlated with the E2 branch in pseudotime and all are currently under investigation as cancer biomarkers." (PMID 30418965, 2018). "Extensive molecular profiling revealed that a number of components of the IGF pathway, including IRS2 and IGFBP5, may play key roles in determining the sensitivity of cancer cells to humanized IGF1R antibody figitumumab." (PMID 28706506, 2017). "IGFBP5 has diverse effects on growth of cancer cells depending on cell type and cell content." (PMID 26569312, 2015). "We can suggest that IGFBP5 may directly or indirectly regulate cancer metastasis pathways through the top differentially expressed genes." (PMID 26569312, 2015). "Other effects of IGFBP-5 have been the focus of research in the cancer field." (PMID 26103640, 2015).
cancer (continued). "To determine whether IGFBP5-inhibited EMTs affect the generation of cancer stem cell (CSC)-like cells, we performed qRT-PCR to analyze the master stem cell transcription factors (TFs) in OE cells." (PMID 26010068, 2015). "Furthermore, the different domains of IGFBP5 exert distinct effects on the tumorigenicity and metastasis of different human cancers." (PMID 26010068, 2015). "Besides the anti-apoptotic effects, IGFBP5 was shown to have stimulatory effects on apoptosis in different cancer types." (PMID 26569312, 2015). "IGFBP5 has several functional roles in carcinogenesis and cancer development, which can determine cell survival and regulate cell growth, migration, and invasion in the development of cancer." (PMID 26010068, 2015). "Thus, we wanted to determine if RASSF1C mediates its effects on cancer cells through interactions with IGFBP-5 and PIWIL1." (PMID 25007054, 2014). "Within this locus, Igfbp5 and Igfbp2 are good candidates for cancer modifier of lung tumorigenesis." (PMID 22973541, 2012). "Moreover, the role of IGFBP5 in cancer progression appears to be context-dependent." (PMID 38351010, 2024). "Hence, the mTORC1/HIF1α/IGFBP5 axis may play a general role in restricting IGF1R-driven PI3K/AKT activity in (breast) cancer cells." (PMID 36093095, 2022). "The microenvironment may also contribute to IGFBP5 production in cancer." (PMID 36093095, 2022). "We found that calcitriol treatment increased expression of IGFBP5 in bulk cancer cells, while decreased its expression in CSCs, suggesting that differential induction of IGFBP5 by calcitriol could be a reason for differential activation of VDR signaling in CSCs and bulk cancer cells." (PMID 29581858, 2018). "Besides these increased IGFBP-5 mRNA levels have been proved to be associated with a poor outcome for the patients who have positive lymph nodes and high circulating concentrations of IGFBP-3 is associated with a lower cancer risk from clinical trail." (PMID 20003295, 2009). "Of the IGFBPs, insulin-like growth factor binding protein 5 (IGFBP5) is the most evolutionarily conserved with a dynamic range of IGF-dependent and -independent functions, and studies on the actions of IGFBP5 in cancer have been somewhat paradoxical." (PMID 36465383, 2022). "MiR-204-5p interaction with the 3'-UTR of IGFBP-5 mRNA leads to IGFBP-5 downregulation, increased apoptosis, and cell cycle arrest, implying an oncogenic role for IGFBP-5 in this cancer." (PMID 35597813, 2022). "These CTCs expressing IGFBP5 also had increased expression of stem cell associated genes aldehyde dehydrogenase 1A2 (ALDH1A2) and Kruppel-like factor 4 (Klf4), which could indicate a cancer stem-like cell phenotype, a state thought to modulate the ability of cancer cells to seed new tumors." (PMID 36465383, 2022). "IGFBP5, the most conserved member of the IGFBP family, is significantly upregulated during the differentiation of several key cell lineages and in human cancer and metastatic tissues." (PMID 32801999, 2020). "TGF-β is another canonical cytokine involved in carcinoma, and the Pearson correlation coefficient between TGF-β and IGFBP5 was 0.41 in our study." (PMID 31886201, 2019). "Using an unsupervised approach that used the whole genome data, given the different kinds of cancers studied within the CCLE project, the sensitivity of cells lines to the IGFR kinase inhibitor AEW541 was also predicted by IGFBP5 expression levels." (PMID 28882129, 2017). "Here, we found mutated genes at the level of the receptor itself in 7% of cases: focal amplification of IGF1R (n=3) and of IGF1 (n=2); frameshift indels in the recessive cancer genes, IGF2R (n=2) and IGFBP5 (n=1)." (PMID 28643781, 2017). "The insulin-like growth factor binding protein 5 (IGFBP5), which is often dysregulated in human cancers, plays a crucial role in carcinogenesis and cancer development." (PMID 26010068, 2015).
cancer (continued). "IGFBP5 is the most conserved binding protein of the IGFBP family in all vertebrates and is frequently dysregulated in human cancers." (PMID 26569312, 2015). "Because the anti-cancer agent, betulinic acid (BA), has been shown to down-regulate PIWIL1 gene expression, we studied the effects of BA and RASSF1C/IGFBP-5 interaction on PIWIL1 gene expression and β-catenin protein levels." (PMID 25007054, 2014). "Involvement of theIGF-1/AKT pathway in cancer cachexia was confirmed by our data showing decreased AKT activation as evidenced bydown-regulated IGF-1, IRS-1 and IGFBP5." (PMID 21069263, 2011). "In comparison to normal tissues, IGFBP5 expression was significantly reduced in all remaining cancers but not statistically different in LAML and SKCM." (PMID 38164271, 2024). "In GSE85195, the expression of IGFBP5 in OLK samples was higher than OSCC samples, and in GSE26549, OLK patients who developed cancer were with a lower baseline expression of IGFBP5 than those who do not." (PMID 38962427, 2024). "In contrast, low-grade cancers had low LAT1 and IGFBP-5 expression (27 of 68 specimens, 39.71%)." (PMID 31992742, 2020). "To determine the complex mechanism by which one cytokine is involved in the progression of carcinoma and to explore the possible mechanism of IGFBP5 in KIRP, we identified two key proteins, VEGFA and TGF-β, which are highly related to IGFBP5 and actively participate in carcinoma." (PMID 31886201, 2019). "However, there are relatively few studies on the expression of IGFBP5 and IGFBL1 in cancer." (PMID 37088808, 2023). "In addition, IGFBPs may play synergistic roles in various cancer-related pathways because a significant correlation was detected, such as IGFBP3-IGFBP4(r = 0.54), IGFBP4-IGFBP7(r = 0.50) and IGFBP5-IGFBP7(r = 0.49)." (PMID 37088808, 2023). "However, few studies have investigated the interaction between IGFBP5 and TGF-β in carcinoma." (PMID 31886201, 2019). "This suggests that Igfbp5 may play a role in the observed decrease in the mesenchymal traits of cancer cells upon TAM depletion; however, further research is required to elucidate the mechanisms involved in the direct regulation of Igfbp5 expression in cancer cells by TAMs." (PMID 38169569, 2024). "IGFBP5 acts through numerous signaling pathways, including but not limited to VEGF, NF-kB, AKT, and TGFβ, each of which may induce an independent phenotype in cancer." (PMID 36465383, 2022).
infection (9 papers, 2016 to 2024). The state of being infected such as from the introduction of a foreign agent such as serum, vaccine, antigenic substance or organism. "As shown in the OCR and ECAR curves for ATP production, IGFBP5‐shRNA infection induced an appreciable increase in the OCR and ECAR." (PMID 38886900, 2024). "HSPA5 KD, PSMA2 KD and IGFBP5 KD remained stable throughout the course of infection." (PMID 36680137, 2022). "In parallel, positive regulators, such as HIF-1α, a master transcriptional regulator of glycolysis, and IGFBP5, capable of activating IGF1R-AKT to increase glycolysis, were significantly upregulated post infection." (PMID 37256871, 2023). "Furthermore, MMP-7 was found in metaplastic lesions in gerbil infection models, which supports the observation that it releases the growth factor IGFII from myofibroblasts by cleaving IGFBP5 (insulin like growth factor binding protein 5)." (PMID 28398251, 2017).
cardiovascular disease (3 papers, 2014 to 2025). "There have also been recent studies on the relationship between IGFBP5 and cardiovascular disease." (PMID 40729024, 2025). "Several studies indicate that the increase in serum IGFBP5 levels increases the risk of cardiovascular disease, but it is not clear how serum IGFBP5 causes the disease." (PMID 40729024, 2025).
heart disease (3 papers, 2014 to 2025). "It was further postulated that IGFBP5 provides a new mode for the regulation of apoptosis associated with MA-associated cardiac diseases." (PMID 25230843, 2014). "High IGFBP5 levels have been associated with the initiation and progression of heart disease." (PMID 40365313, 2025).